HULC (hepatocellular carcinoma up-regulated long non-coding RNA)
Diseases named in the same sentence as HULC in open-access papers (continued):
Sharing a sentence is not in itself a finding about the gene and the disease.
hepatocellular carcinoma (continued). "Later, a number of lncRNAs, such as HULC and MALAT1, are connected to the development of hepatocellular carcinoma (HCC) because of their functions in metastasis, apoptosis resistance, and cellular proliferation." (PMID 40868128, 2025). "In addition, it was found that lncRNA HULC plays a role as the ceRNA of miR-3200-5p in hepatocellular carcinoma, and miR-3200-5p can regulate the ferroptosis process by targeting ATF4 and inhibit the proliferation and metastasis of hepatoma cells." (PMID 36408273, 2022). "Thus, HULC can not only increase the expression of P62 by reducing mature miR-15a, but also increase autophagy by increasing Sirt1-dependent LC3II to promote the development of hepatocellular carcinoma." (PMID 35183058, 2022). "Hepatocellular Carcinoma Up-regulated Long Non-coding RNA (HULC) and Clock circadian regulator (CLOCK) mRNA 5′-UTR have a complementary base paring region, and the results of luciferase reporter gene assays suggest that HULC can improve the stability of CLOCK mRNA." (PMID 31097003, 2019). "HULC upregulates the transcriptional factor peroxisome proliferator-activated receptor alpha (PPARA) which increases acyl-CoA synthetase long-chain family member 1 (ACSL1), leading to triglycerides and cholesterol production and proliferation of hepatoma cells." (PMID 28840253, 2018). "Given that HULC promotes autophagy by enhancing the autophagy process of the transformation from LCI to LC3 II (a autophagy marker), we try to test whether that HULC promotes the growth of hepatoma cells by targeting this process." (PMID 29895332, 2018). "Moreover, the expression of lncRNA HULC, regulated by miR-6825-5p, miR-6845-5p, and miR-6886-3p, elevates the deubiquitination effect of USP22 on SIRT1, making hepatocellular carcinoma (HCC) cells resistant to oxaliplatin and inducing protective autophagy in HCC cells." (PMID 38702734, 2024).
liver cancer (81 papers, 2011 to 2025). An epithelial or non-epithelial malignant neoplasm that arises from the liver. "HULC (highly upregulated in liver cancer), encoded on chromosome 6p24.3, was first identified in HCC samples as a novel lncRNA markedly upregulated compared to non-tumor liver tissue samples." (PMID 40699747, 2025). "lncRNA HULC is specifically and highly upregulated in liver cancer, and it is associated with intrahepatic metastases, HCC recurrence, and postoperative survival." (PMID 34104647, 2021). "This assertion is based on several observations: 1) HULC is negatively associated with miR15a expression in human liver cancer tissues." (PMID 29895332, 2018). "lncRNA HULC (highly upregulated in liver cancer) and lncRNA PTCSC3 (papillary thyroid carcinoma susceptibility candidate 3) are two classic cases in this field, highlighting different roles of miRNA–lncRNA competitive interactions." (PMID 29340250, 2018). "MALAT1 is elevated in the whole blood of metastatic lung cancer patients, and HULC, detected in the blood, is also proposed as a diagnostic biomarker both for liver cancer and gastric cancer." (PMID 29416704, 2018). "HULC (Heptacellular carcinoma up-regulated long non-coding RNA) is known to be upregulated in liver cancer and associated with tumorigenesis." (PMID 30567492, 2018). "Finally, the RBP IGF2BP1 (IGF2 mRNA-binding protein-1) destabilizes the liver-cancer-associated lncRNA HULC (Highly Upregulated in Liver Cancer) in a CNOT1-dependent manner." (PMID 39941720, 2025). "Given that HULC promotes the growth of liver cancer stem cells and miR675 is associated with oncogenesis, we consider whether HULC regulates the expression of miR675." (PMID 31900225, 2020). "HULC is negatively associated with expression of PTEN or miR15a in patients of human liver cancer." (PMID 29895332, 2018). "To address whether HULC was associated with autophagy, we analyse the HULC functions on autophagy in liver cancer cells." (PMID 29895332, 2018). "The present study depicts a novel provides evidence for HULC to play hepatocarcinogenesis roles by downregulating PTEN in liver cancer cells, which might be one of the mechanisms underlying the HULC in hepatocarcinogenesis and may have potential therapeutic significance." (PMID 29895332, 2018). "Studies have demonstrated that HULC plays a critical role in promoting the progression of liver cancer by interacting with genes, RNA, and proteins." (PMID 40909946, 2025). "We found that LXR alpha and high expression of liver cancer transcript (highly upregulated in liver cancer, HULC) cut the HULC promoter region, combining expression, thereby lowering fork frame M1 (FOXM1) expression." (PMID 41179299, 2025). "For example, in liver cancer, HULC directly binds to miR-372, leading to miR-372 decreased expression and activity." (PMID 40909946, 2025). "In a liver cancer xenograft model, overexpression of HULC increased regulatory T cell (Treg) proliferation and upregulated PD-1 expression in the tumor microenvironment." (PMID 40909946, 2025). "Conversely, HULC inhibits miR-372 activity, leading to upregulation of HULC expression in liver cancer." (PMID 40909946, 2025). "LncRNA HULC (Highly Upregulated in Liver Cancer) can bind to the transcription factor CREB, enhancing its activity and promoting the expression of genes involved in cell proliferation and survival." (PMID 39211780, 2024). "This leads to increased cell proliferation and tumorigenicity, highlighting the oncogenic potential of HULC in liver cancer." (PMID 39156976, 2024). "Another study found that liver cancer cell ferroptosis can be induced by suppressing HULC, mediated by the miR-3200-5p/ATF4 axis." (PMID 39267831, 2024). "HULC (Highly Upregulated in Liver Cancer) is a notable lncRNA that acts as a molecular sponge for miR-372, which directly targets the PI3K/AKT pathway." (PMID 39156976, 2024).
liver cancer (continued). "In liver cancer, an increase in the lncRNA HULC, driven by the protein CREB, significantly influences cellular mechanisms by altering YB-1 phosphorylation patterns, which is key in hepatocarcinogenesis." (PMID 37759495, 2023). "For instance, circulating LINC00152, HULC and UCA1 have been associated with gastric and liver cancer, two organs that are in close proximity within the upper abdomen and which both originate from the foregut of the embryonic endoderm." (PMID 35729321, 2022). "In 2007, the expression of lncRNA HULC was first found to be significantly elevated in peripheral blood cells of 75% of patients with liver cancer." (PMID 36203765, 2022). "For example, HULC (highly upregulated in liver cancer), a 1.6-kb oncogenic lncRNA, is overexpressed in HCC." (PMID 36031658, 2022). "For instance, the plasma level of lncRNA HULC (highly upregulated in liver cancer) has been reported to be useful for HCC diagnosis and prognosis." (PMID 35141283, 2022). "MALT1 dysregulation together with another lncRNA, HULC (highly upregulated in liver cancer), promotes the growth of liver cancer stem cells." (PMID 34439391, 2021). "For instance, lncRNA HULC is specifically expressed in hepatocytes and highly upregulated in liver cancer." (PMID 34104647, 2021). "Our present results are consistent with these reports and provide novel evidence for a suppressor role of CircMEG3 in inhibiting malignant growth of liver cancer via altering HULC." (PMID 33425489, 2021). "Previous studies have shown that the lncRNA HULC expression is upregulated in liver cancers, colon cancer, ovarian cancer, and other tumor tissues and is associated positively with tumor size, TNM stage, chemotherapy resistance, and poor prognosis." (PMID 34213079, 2021). "The lncRNA HULC (highly up-regulated in liver cancer) has also been shown to drive ERK-mediated YBX1 phosphorylation, thereby increasing the transcription of oncogenic genes in HULC-expressing cells." (PMID 34266873, 2021). "For instance, HULC overexpression promotes liver cancer development and invasion via sponging miR-372." (PMID 32437330, 2020). "This group further reported that LncRNA HULC rs7763881 and MALAT rs619586 were associated with decreased susceptibility of Egyptian hepatitis virus-persistent carriers to liver cancer." (PMID 33659210, 2020). "In this study, our observations suggest that HULC promotes progression of liver cancer stem cells dependent on CyclinD1." (PMID 31900225, 2020). "An example of such regulation is exemplified by HULC, an lncRNA upregulated in liver cancer, whose upregulated expression is in part to its inhibitory effects on the expression and activity of miR-372." (PMID 32678830, 2020). "In particular, CyclinD1 is required for the oncogenic functions of HULC in human liver cancer stem cells." (PMID 31900225, 2020). "Collectively, these results suggest that HULC promotes the growth in vitro of liver cancer stem cells." (PMID 31900225, 2020). "Hepatitis B virus X protein (HBx) activated the lncRNA highly upregulated in liver cancer (HULC) promoter through cAMP-responsive element-binding protein (CREB), thereby upregulating HULC expression in liver cancer HepG2 cells." (PMID 32709848, 2020). "In conclusion, our study found that HULC promotes the progression of liver cancer via the HULC/miR-2052/MET axis, providing a potential diagnostic and therapeutic target for HCC." (PMID 31645479, 2019). "Previous studies illustrated that HBx-mediated HULC upregulation promotes the increase of mRNA and protein levels in liver cancer by downregulating the tumor suppressor gene CDKN2C (p18)." (PMID 31341758, 2019). "HULC (highly upregulated in liver cancer) is a 16 kb lncRNA at chromosomal location 6p24.3 and is has been shown to be overexpressed in patients with liver cancer." (PMID 31231228, 2019).
liver cancer (continued). "It has been reported that lncRNA HULC serves as scaffold for YB-1 and its downstream gene to modulate the development of liver cancer." (PMID 31695772, 2019). "We demonstrate that HULC is negatively associated with PTEN and miR15a expression in human liver cancer tissues." (PMID 29895332, 2018). "Of significance, our observations also revealed that HULC inhibited PTEN through ubiquitin–proteasome system mediated by autophagy-P62.Ultimately,HULC activates AKT-PI3K-mTOR pathway through inhibiting PTEN in human liver cancer cells." (PMID 29895332, 2018). "Collectively, these findings suggest that HULC accelerates malignant progression of liver cancer cells." (PMID 29895332, 2018). "In additional, CUDR overexpression enhanced the loading of pStat3 on the promoter region of HULC which increased HULC expression in the liver cancer." (PMID 29895332, 2018). "Herein, the involvement of HULC promotion of liver cancer cell growth is supported by results from two parallel sets of experiments: 1) HULC was over-expressed in human liver cancer tissue." (PMID 29895332, 2018). "To identify the relationship between HULC and PTEN, miR15a in human liver cancer, we detected the expression of HULC, miR15a, PTEN in human hepatocarocinoma tissues." (PMID 29895332, 2018). "Strikingly, we demonstrated that HULC promotes autophagy in liver cancer cells and the involvement of HULC promotion of autophagy is supported by results from three parallel sets of experiments: 1) HULC increased the expression of LC3 (a autophagy marker)." (PMID 29895332, 2018). "For example, HULC acted as an endogenous sponge to downregulate the miR-372 expression in liver cancer." (PMID 28969024, 2017). "This process resulted in alterations of chromatin organization and increased expression of HULC, thus showing that HULC was involved in an autoregulatory loop that mantained its abundant expression in liver cancer." (PMID 29147648, 2017). "HULC (Highly Upregulated in Liver Cancer) was first reported in liver cancer and showed extensive regulatory functions in cell proliferation, apoptosis, invasion, cell cycle, and drug resistance." (PMID 28199963, 2017). "In summary, our present data indicated that HULC combined with MALAT1 promotes liver cancer stem cells malignant progression through altering telomere and MSI, with diagnostic and prognostic implications." (PMID 27782152, 2016). "Collectively, TRF2 knockdown abrogated the oncogenic function of the MALAT1 plus HULC in liver cancer cells." (PMID 27782152, 2016). "HULC, as a Sp-regulated gene, was important for liver cancer cell growth, migration, invasion and EMT." (PMID 27285757, 2016). "It is worth noting that our findings in this study provide novel evidence for an active role of HULC plus MALAT1 promotion of liver cancer stem cell growth." (PMID 27782152, 2016). "Our demonstrations suggest that haploinsufficiency of HULC/MALAT1 plays an important role in malignant growth of liver cancer stem cell." (PMID 27782152, 2016). "Taken together, we conclude that HULC promotes tumor angiogenesis in liver cancer through miR-107/E2F1/SPHK1 signaling." (PMID 26540633, 2016). "Wang and his colleagues showed that the crosstalk between lncRNA HULC and PRKACB gene via competitive binding to miR-372 in a ceRNA-dependent feed-forward loop resulted in highly up- regulated expression of HULC in liver cancer." (PMID 27487139, 2016). "In summary, in this study we report that HULC is able to promote the tumor angiogenesis through miR-107/E2F1/SPHK1 signaling in liver cancer." (PMID 26540633, 2016). "In this study, we show that HULC is an Sp-regulated gene and that the functional pro-oncogenic activities of HULC and Sp transcription factors are similar in liver cancer cells." (PMID 26317792, 2015).
liver cancer (continued). "We also further characterized the role of HULC in liver cancer by examining the modulation of gene expression after knockdown of HULC or knockdown of two important components of chromatin-modifying complexes (MLL1 and EZH2)." (PMID 26317792, 2015). "In HBV-related liver cancer, HBx induces upregulation of HULC, which in turn suppresses the expression of p18 and facilitates proliferation of HCC." (PMID 24757675, 2014). "A recent paper began to elucidate the mechanism of upregulation of HULC in liver cancer cells, and to provide a potential mechanism of HULC function." (PMID 21489289, 2011). "Furthermore, radioactive in situ hybridization confirmed the elevated expression of HULC in liver cancer tissues." (PMID 40909946, 2025). "Together, PTEN determined the carcinogenic function of HULC in liver cancer cells." (PMID 36213832, 2022). "Therefore, HULC oncogenic action is associated with PKM2, CyclinD1, pRB, P21 WAF1/CIP1, and cellular autophagy in human liver cancer stem cells." (PMID 31900225, 2020). "HULC promotes lipogenesis and cell proliferation, induces apoptosis and enhanced epithelial-mesenchymal transformation (EMT), and also increases the risk of liver cancer development and metastasis." (PMID 31341758, 2019). "HULC was the first identified lncRNA that was specifically overexpressed in liver cancer." (PMID 31645479, 2019). "In this study, we show that lncRNA HULC is upregulated in human liver cancer." (PMID 31645479, 2019). "Furthermore, HULC activates AKT-PI3K-mTOR pathway through PTEN reduction dependent on autophagy in human liver cancer cells." (PMID 29895332, 2018). "Thus, miR15a functions as a key tumor suppressor which inhibits the HULC action in liver cancer cells." (PMID 29895332, 2018). "This study elucidates a novel tumorigenesis mechanism for HULC in liver cancer cells." (PMID 29895332, 2018). "Taken together, PTEN determines oncogenic function of HULC in liver cancer cells." (PMID 29895332, 2018). "Furthermore, lncRNA UCA1 also induces the expression of lncRNA HULC (highly upregulated in liver cancer) in liver cancer and lncRNA HULC in turn stimulates the activity of the Wnt-β-catenin pathway." (PMID 29967761, 2018). "Our study also demonstrated that other SNPs were correlated with overall cancer risk, namely, metastasis-associated lung adenocarcinoma transcript 1 (MALAT1, rs619586 A/G), HOXA distal transcript antisense RNA (HOTTIP, rs1859168 A/C), and highly up-regulated in liver cancer (HULC, rs7763881 A/C)." (PMID 29802154, 2018). "In addition, the expression of lncRNA HULC is involved in an auto-regulatory loop in which it's inhibitory to expression and activity of miR-372 allows HULC upregulated expression in liver cancer." (PMID 25760077, 2015). "In summary, this study demonstrates that Sp1 and other Sp transcription factors are important for liver cancer cell growth, migration, survival, invasion and epithelial-mesenchymal-transition, and we demonstrate that HULC and other lncRNAs are Sp-regulated genes in HCC." (PMID 26317792, 2015). "Their data elucidated that fine tuning of the expression of the lncRNA HULC is part of an auto-regulatory loop, in which the inhibitory effect of HULC on the expression and activity of miR-372 allows upregulated expression of HULC in liver cancer." (PMID 24888564, 2014). "Depletion of HULC resulted in a significant deregulation of several genes involved in liver cancer." (PMID 24757675, 2014). "Therefore, HULC activates AKT-PI3K-mTOR pathway through PTEN reduction in human liver cancer cells." (PMID 29895332, 2018).